ELOA2 (elongin A2)
Description:
SIII, also known as elongin, is a general transcription elongation factor that increases the RNA polymerase II transcription elongation past template-encoded arresting sites. Subunit A2 is transcriptionally active but its transcription activity is not enhanced by binding to the dimeric complex of the SIII regulatory subunits B and C (elongin BC complex).
Synonyms: TCEB3B; TCEB3L; HsT832
Tractability: No criterion of Open Targets' tractability assessment is met for any kind of drug.
Gene: Protein-coding gene on chromosome 18 (47,032,527 to 47,035,621, reverse strand). Ensembl gene ENSG00000206181.
Subcellular location: Nucleus
Subcellular location (Human Protein Atlas): Nucleoplasm; Cytosol; Nucleoli
Pathways (Reactome):
Disease: Formation of HIV elongation complex in the absence of HIV Tat; Formation of HIV-1 elongation complex containing HIV-1 Tat; HIV elongation arrest and recovery; Pausing and recovery of HIV elongation; Pausing and recovery of Tat-mediated HIV elongation; Tat-mediated HIV elongation arrest and recovery; Tat-mediated elongation of the HIV-1 transcript
Gene expression (Transcription): Formation of RNA Pol II elongation complex; RNA Polymerase II Pre-transcription Events; RNA Polymerase II Transcription Elongation
Gene Ontology:
Molecular function: protein binding
Biological process: regulation of DNA-templated transcription elongation; transcription by RNA polymerase II; regulation of DNA-templated transcription; transcription elongation by RNA polymerase II
Cellular component: nucleoplasm; elongin complex; nucleus
Genetic constraint (gnomAD): Loss-of-function variants: 3 observed, 3.15 expected, observed/expected ratio (o/e) 0.95, 90% interval 0.41 to 1.84. That is too few expected variants to judge how well the gene tolerates losing a copy. Missense variants: 1,271 observed, 1,032.2 expected, observed/expected ratio (o/e) 1.23, 90% interval 1.17 to 1.29. Synonymous variants: 497 observed, 420.64 expected, observed/expected ratio (o/e) 1.18, 90% interval 1.1 to 1.27.
Homologues: Orthologues: chimpanzee ELOA2 (70% identical), macaque ELOA2 (56% identical), tropical clawed frog eloa (32% identical), Drosophila melanogaster EloA (19% identical), zebrafish eloa (16% identical), rat Eloa2l (13% identical), Caenorhabditis elegans tceb-3 (12% identical). Paralogues in human: ELOA (49% identical).
Diseases named in the same sentence as ELOA2 in open-access papers:
ELOA2 is named in the same sentence as 4 diseases in open-access papers, as found by Europe PMC text mining. Sharing a sentence is not in itself a finding about the gene and the disease. The quoted sentences say what the papers report.
Anophthalmia (1 paper, 2024). Absence of the globe or eyeball. "ELOA2 does not have a murine analog; however, Eloa knockout results in abnormal eye morphology, anophthalmia, and abnormal vitreous body morphology." (PMID 39584991, 2024).
ELOA2 also shares sentences with these, for which no sentence is quoted: lymphoma (1 paper); neuroblastoma (1); renal cell carcinoma (1).